XBP1 (X-box binding protein 1)
Diseases named in the same sentence as XBP1 in open-access papers (continued):
Sharing a sentence is not in itself a finding about the gene and the disease.
infection (continued). "Following the infection of fibroblasts with XBP1-s lentivirus and a control vector lentivirus, comparable levels of GFP expression were observed in fibroblasts, indicating similar infection efficiencies." (PMID 38534372, 2024). "Another study has clarified that the infection can skew the macrophage polarization toward M2-like TAMs and stimulate IRE1α/XBP1, thereby accelerating the release of pro-tumorigenic cytokine." (PMID 38554175, 2024). "In this study, we examined the role of IRE1α and XBP1 during infection with the human betacoronaviruses, HCoV-OC43 and SARS-CoV-2." (PMID 37306512, 2023). "While IRE1α, XBP1, and TLR4 KO macrophages all showed reduced glycolysis during infection, only the IRE1α-deficient macrophages showed a reduced bacterial burden, suggesting that IRE1α supports B. abortus replication independently of enhanced glycolysis." (PMID 36475773, 2023). "Together, these data demonstrate that SARS-CoV-2 requires host IRE1α RNase activity and XBP1 for optimal infection." (PMID 37306512, 2023). "IRE1α activation and XBP1 target gene induction also occur during infection with the avian gammacoronavirus and infectious bronchitis virus (IBV)." (PMID 37306512, 2023). "The ATF6α sensor is robustly activated during infection while the IRE1α-XBP1 branch is down-regulated." (PMID 37434252, 2023). "Here, we demonstrate that the host proteins IRE1α and XBP1 are required for robust infection by the human coronaviruses, SARS-CoV-2 and HCoV-OC43." (PMID 37306512, 2023). "The IRE1α-XBP1 signaling axis supports this glycolytic switch in macrophages when activated by lipopolysaccharide (LPS) stimulation or infection with the intracellular bacterial pathogen Brucella abortus." (PMID 36475773, 2023). "We found that IRE1α is activated and promotes infection via XBP1 during infection of cultured cells with both viruses." (PMID 37306512, 2023). "The human betacoronavirus SARS-CoV inhibits IRE1α activation resulting in minimal XBP1 splicing during infection." (PMID 37306512, 2023). "In contrast, EV-D68 infection reduced XBP1 levels compared to the mock-infection control, indicating that the virus does not trigger ER stress in H1HeLa cells." (PMID 37850626, 2023). "Ire1 phosphorylation and an upregulated overall Xbp1 mRNA level was detected a few hours after EV-71 infection of RD cells." (PMID 36366584, 2022). "MERS-CoV, however, induced increasing XBP1 splicing over the course of infection, matching the results in A549 and Calu-3 cells." (PMID 36125275, 2022). "Our analysis revealed the complicated dynamics of Ire1 autophosphorylation and cleavage during infection, as well as the virus-mediated repression of Xbp1 mRNA splicing in infected cells." (PMID 36366584, 2022). "CVB3 was also shown to trigger ER stress: upon CVB3 infection, ATF6 and Xbp1 were activated via protein cleavage and mRNA splicing, respectively, but all of these changes occurred at the late stages of infection (12 h post-infection, hpi)." (PMID 36366584, 2022). "While XBP1 mRNA unconventional splicing in neuronal SH-SY5Y cells was similar after infection with both TBEV strains, it was faster and more pronounced in Caco-2 cells upon infection with TBEV HB171." (PMID 34834970, 2021). "IBV induced ER stress in infected cells and activated the IRE1α-XBP1 pathway at a late stage of infection." (PMID 35003039, 2021). "Studies using MHV have demonstrated that the IRE1 axis also senses ER stress during infection, as shown by efficient splicing of XBP1 mRNA upon infection or overexpression of the S protein." (PMID 33996638, 2021). "In larvae subjected to sterile injury or infection with Enterococcus faecalis, levels of spliced Xbp1 were increased between 1.3- to 1.9-fold compared with uninfected controls at 6, 18, 24, and 36 hours following infection." (PMID 33227003, 2020). "MCMV activates the IRE1-XBP1 pathway early post infection to relieve repression by XBP1u, the product of the unspliced Xbp1 mRNA." (PMID 32065579, 2020).
infection (continued). "We detected a short and transient increase of XBP1 splicing between 5 and 7 hr post infection (hpi)." (PMID 32065579, 2020). "In HeLa cells, YIPF5 has been shown to interact with and promote IRE1 oligomerization and phosphorylation and enhance downstream XBP1 splicing upon tunicamycin exposure or infection with Brucella abortus." (PMID 33164986, 2020). "Subsequently, Xbp1-luc and pRL-TK were cotransfected into Marc-145 cells, followed by mock infection or infection with PRRSV at an MOI of 0.5." (PMID 32753633, 2020). "This transient event allows viral protein synthesis and accumulation that finally trigger UPR by IRE1-XBP1 (X-box binding protein 1) axis in the mid-phase of infection." (PMID 32661235, 2020). "Reports in human fibrosarcoma cells showed UPR activation in a time-dependent manner; with PERK induced at early stages of infection, followed by the IRE1α-XBP1 axis and, finally, ATF6 in mid and late replication cycle stages." (PMID 32106582, 2020). "Infection of mice with Lymphocytic choriomeningitis virus resulted in upregulation of spliced Xbp-1, and Xbp-1 enhanced differentiation of CD8+ T cells." (PMID 30978945, 2019). "We assessed the effect of HRV16 infection (MOI = 5) on IRE1 activity at 3 h, 6 h and 9 h post-infection using specific RT-PCR primers to distinguish between the unspliced (inactive, XBP1u) and spliced (active, XBP1s) forms of the XBP1 transcript." (PMID 30717233, 2019). "MCMV and HCMV induce IRE1 activation and XBP1 splicing early in infection, but at later stages of lytic replication IRE1 is downregulated, which impedes XBP1 splicing." (PMID 31877732, 2019). "This work is of particular interest as Xbp-1 appears to promote CD8+ T cell effector functions in response to infection." (PMID 30978945, 2019). "XBP1s mRNA was detected in DEV-infected DEF cells at 36 hours post-infection, while unspliced XBP1 mRNA was found in mock infected cells at the same point, which indicated that DEV infection activated the IRE1-XBP1 pathway under ER stress." (PMID 29272280, 2017). "Taken together, DENV2 activates XBP1 at earlier stage of infection, followed by upregulating BiP/GRP78 in mosquito cells." (PMID 29098151, 2017). "The authors concluded that the activation of XBP1 has an important role in infection by increasing IFN-β expression and protecting the parasites from oxidative stress, thereby promoting parasite proliferation." (PMID 28883998, 2017). "These include the xbp1 gene, which was upregulated following infection with all three pathogens (although only differentially expressed following A. phagocytophilum or LIV infection), consistent with the activation of an innate immune response." (PMID 28202075, 2017). "For instance, the activation of XBP-1 in hepatocytes infected by P. berghei favor the infection by the parasite through the modulation of lipid synthesis." (PMID 27499755, 2016). "Titers derived from XBP-1 KO cells decreased substantially compared to those derived from WT cells at 1 day post infection (dpi)." (PMID 25333725, 2014). "For instance, the induction of Xbp-1 splicing after infection with JEV, TBEV, and USUV, the expression of CHOP during JEV infection, and the cleavage of ATF6 in TBEV-infected cells have been described." (PMID 24917859, 2014). "In contrast, knockdown of XBP1 via shRNA lentiviral infection slightly increased the basal level of cell apoptosis but significantly augmented H2O2-induced HUVECs apoptosis even at a low concentration (20 μmol/liter)." (PMID 25190803, 2014). "Knockdown of XBP1 via shRNA lentiviral infection not only abolished flow-induced but also decreased the basal level of Akt1 phosphorylation and HO-1 expression." (PMID 25190803, 2014). "Overall we were able to demonstrate that systemic deletion of XBP-1 prior to infection attenuates MCMV ability to propagate in vivo during acute infection." (PMID 25333725, 2014).
infection (continued). "To validate that this reduction can be attributed to viral-induced deletion of XBP-1 we analyzed the XBP-1 locus throughout the infection and observed recombination as early as 4 hpi." (PMID 25333725, 2014). "In IBV-infected Vero cells, significant splicing of XBP1 mRNA was detected starting from 12 to 16 h post-infection till the late stage of infection." (PMID 24987391, 2014). "Here we show that deletion of XBP-1 prior to or early after infection confers a transient delay in viral propagation in fibroblasts that can be overcome by increasing the viral dose." (PMID 25333725, 2014). "Real time PCR analysis revealed the increase in transcription of XBP-1 gene starting from 3 h post infection and significant increase in the EDEM transcript at 24 h (~2.5 fold) and 48 h (~24 fold) post infection." (PMID 23356742, 2013). "The data shows that CHIKV infection triggers moderate XBP-1 splicing from 12 h post infection, which only becomes prominent at 48 h post infection." (PMID 23356742, 2013). "In C. elegans, innate immunity pathways were shown to be physiologically relevant inducers of ER stress, where activation of the response to infection with certain bacteria induces XBP-1-dependent UPR responses." (PMID 23724040, 2013). "In NIH-3T3 fibroblasts (expressing only endogenous IRE1), splicing of Xbp1 transcripts and transcription of ERdj4 was strongly inhibited upon infection with the MCMV control virus, but only moderately diminished upon infection with MCMVΔM50." (PMID 23950715, 2013). "Apart from the strong inhibition of the IRE1-XBP1 axis at late times postinfection, MCMV infection causes a modest induction of Xbp1 mRNA splicing at very early times after infection (2 hpi), which decreases within the following hours." (PMID 23950715, 2013). "Infection of the xbp-1 mutant with P. aeruginosa leads to disruption of ER morphology and larval lethality." (PMID 22359644, 2012). "Only the XBP-1 pathway was significantly activated in cells infected with rSARS-CoV-ΔE compared to infection with the wt virus." (PMID 22028656, 2011). "We noticed a hybrid form of XBP1 mRNA (hXBP1) upon treatment with 2 μM TG and upon Dengue infection (24 h post-infection and thereafter)." (PMID 17888185, 2007). "Our data suggest that the IRE1α pathway could be activated at the late stage of infection when high levels of the total XBP1 gene and the downstream EDEM1 gene were detected." (PMID 40248709, 2025). "Interestingly, we observed that both IRE1 and XBP1 were sequestered to the viral replication sites during infection." (PMID 41157563, 2025). "However, BLOC1S1, SCARA3, COL6A1, and HGSNAT were unaffected by HCoV-OC43, suggesting that IRE1α activity is limited to XBP1 splicing during infection." (PMID 37306512, 2023). "In addition, infection generates an oxidative environment beneficial to virus replication, which in turn results in stress to induce XBP1 splicing and induction of downstream effectors essential for viral replication complex formation." (PMID 37164963, 2023). "Nonetheless, decreasing full-length XBP1 and BiP levels during infection may be a common strategy employed by enterovirus to avoid ER stress, which, as we have shown, is a negative for non-lytic release." (PMID 37850626, 2023). "To better understand the host epithelial response to coronavirus infection, we systematically compared the activation of the IRE1α/XBP1 pathway of the UPR during infection with betacoronaviruses in lung-derived A549 and Calu-3 cells lines and iPSC-derived AT2 cells." (PMID 36125275, 2022). "We sought to investigate if ICOV induces IRE1a/XBP1 signaling during the infection." (PMID 36146755, 2022). "LGTV induced XBP1 expression even later at 72 h post infection, which could be explained by the delay in replication." (PMID 34834970, 2021).
infection (continued). "The induction of the IRE1 activation marker XBP1 in intestinal Caco-2 cells appeared earlier after infection with TBEV HB171 with a protein band becoming visible already at 24 h post infection, which correlates with the naturally observed tropism of this virus strain." (PMID 34834970, 2021). "Interestingly, treatment of Z-VAD-fmk to the ZIKV infected cells showed dramatic increase in XBP1 splicing, and however treatment of salubrinal showed a moderate increase in XBP1 splicing compared to the 0.1rMRV infection alone." (PMID 33500388, 2021). "Similarly, in macrophages, phosphatidylcholine synthesis and Xbp1 activation are necessary for maximal levels of cytokine secretion in response to infection or LPS stimulation." (PMID 33227003, 2020). "Finally, we demonstrate that inducible genetic disruption of IRE1α and XBP1 impairs ZIKV replication in a mouse model of infection." (PMID 32138181, 2020). "Meanwhile, compared with mock infection, BoHV-1 infection induced higher mRNA levels of the XBP1s downstream target ER-localized DnaJ homologue 4 (ERdj4) gene, which further confirmed the XBP1 splicing." (PMID 32887282, 2020). "Furthermore, the IRE1a-XBP1 pathway is required for neutrophil extracellular trap formation during infection Overall, the IRE1a-XBP1 pathway is known to promote neutrophil recruitment and function." (PMID 32850317, 2020). "Thus, the decrease of p-IRE1 made it difficult to exert the endoribonuclease activity to cleave a 26-bp intron from the XBP1 transcript during HRV16 infection." (PMID 30717233, 2019). "Using primers that specifically detect the spliced or unspliced form of XBP1, we found that XBP1 splicing was increased approximately 10-fold at 48 h post-infection; only a modest induction (~ 2-fold increase) of unspliced XBP1 was observed at 24 h post-infection." (PMID 30670030, 2019). "ATF6-dependent genes, such as Xbp1 and BiP, also increased following infection." (PMID 31467282, 2019). "Since XBP1 splicing and modulation of immune response are among the effects induced by Leishmania infection, we considered miR-346 an interesting target to investigate in our infection model." (PMID 29867904, 2018). "Another study observed that hepatitis C virus suppressed the IRE1α-XBP1 pathway during infection." (PMID 28832521, 2017). "Likewise, intestinal-specific RNAi of xbp-1 enhanced sensitivity to PA14 infection, whereas epidermal- and muscular specific RNAi of xbp-1 failed to affect the survival of worms." (PMID 25569229, 2015). "However, in contrast to XBP-1, analysis of MCMV progression in ATF4 deficient hosts indicated a defect at late times p.i., a time that probably corresponds to the second round of infection." (PMID 25333725, 2014). "Indeed, ERAD activation, as demonstrated by XBP1 splicing and upregulation of EDEMs mRNAs, clearly exists during infection of Huh7.5.1 with JFH1." (PMID 24904547, 2014). "As expected, these effects were totally abolished by XBP1 knockdown via shRNA lentiviral infection." (PMID 25190803, 2014). "A priori deletion of XBP-1 resulted in a similar retardation of infection as seen in fibroblasts." (PMID 25333725, 2014). "Our data show that while at the early stages of infection IRE1 is important by executing XBP-1 splicing, at later times when the cells are committed to viral protein synthesis and generation of viral progeny, IRE1 becomes toxic and the virus targets it for degradation." (PMID 25333725, 2014). "Interestingly, although XBP-1 mRNA was spliced upon infection with HCMV, its target genes involved in protein degradation were not expressed." (PMID 25333725, 2014). "At MOI 10 the onset of XBP1 splicing was observed even at 12hr post infection onwards." (PMID 24086645, 2013). "Increased rate of XBP1 splicing was observed in 24 hr, 48 hr and 72 hrs post infection." (PMID 24086645, 2013). "XBP-1 splicing followed a similar wave pattern, which reached a peak at day 3 post infection." (PMID 21949742, 2011).
infection (continued). "In summary, we showed that the Ire1-Xbp1 pathway is modulated in enterovirus-infected cells through a multifaceted mechanism, including autophosphorylation and proteolytic cleavage of Ire1 at the middle stage of infection that coincides with the inhibition of Xbp1 mRNA splicing." (PMID 36366584, 2022). "Further assessed by biochemical experiments, the transcription and protein levels of ER stress markers BiP and CHOP, as well as the levels of XBP1 splicing and eIF2α phosphorylation, were significantly increased by CdhM, confirming that CdhM could induce ER stress alone or during infection." (PMID 35444960, 2022). "Within 12 h of infection, Toxoplasma increased activation of PERK as measured by its self-phosphorylation (PERK-P), induced expression of ATF6 and formation of its cleavage product ATF6-N, and increased levels of the IRE1-derived spliced variant of XBP1 (XBP1s)." (PMID 32636244, 2020). "Interestingly, the NPS3 protein was identified as the primary determinant, but the splicing of XBP1 was always studied in the context of infection; ectopic expression of NSP3 should be tested to better understand all the determinants necessary to modulate splicing." (PMID 31034770, 2019). "Third, longitudinal profiling of ER stress dynamics (e.g., GRP78, p-IRE1, XBP-1, and CHOP at early, mid-, and late infection stages) is warranted." (PMID 40598575, 2025). "To understand the activation of UPR by any of these pathways, we used confocal microscopy and quantified the translocation of downstream transcription factors, such as XBP1, ATF4, and ATF6, inside the nucleus upon infection." (PMID 40272166, 2025). "Infection of IAV induced ERS and activated IRE1/XBP1 signaling pathway to degrade SOD and Sp1 through the ERAD pathway." (PMID 37483299, 2023). "We find that infection with MERS-CoV, OC43, and MHV leads to phosphorylation of IRE1α and the consequent production of spliced XBP1 (XBP1s) transcription factor." (PMID 36125275, 2022). "Direct infection of BMDCs by Toxoplasma gondii induced IRE1α activation via MyD88-dependent TLR signaling, with decreased cross-presentation on XBP1 KO with partial IRE1α disruption." (PMID 35446348, 2022). "Dengue virus also temporally regulate the UPR by triggering transient PERK-eIF2α phosphorylation during the early phase and IRE1α-XBP1 and ATF6 during mid-phase and late phase of infection." (PMID 34106769, 2021). "While XBP1 was readily detectable after 24 h in TBEV Neudoerfl infected cells and peaked at 48 h post infection, XBP1 became apparent only at 48 h post infection in TBEV HB171-infected cells." (PMID 34834970, 2021). "Taking this into account, transcriptomic analysis resulted in an increase in XBP1, IRE1α, CHOP, ATF6, ATF4, PERK, EIF2α and BIP expression after infection with NOX5-β adenovirus at all time conditions." (PMID 33572841, 2021). "Our results indicate that IRE1α and XBP1 are required for optimal ZIKV replication, both in cultured cells and in a mouse model of infection." (PMID 32138181, 2020). "Usutu virus (USUV) infection also induces the UPR, as revealed by the induction of XBP1 mRNA splicing following USUV infection." (PMID 30670030, 2019). "For example, herpes simplex virus-1 (HSV-1) suppresses IRE1-dependent UPR at early stages of infection through the action of the viral protein UL41, which degrades XBP1 mRNA via its RNase activity." (PMID 31495285, 2019). "Because AAV-mediated gene expression in RGCs normally takes at least 2 weeks after infection, CHOP inhibition and XBP-1 activation are likely to occur 2–3 weeks after MOG immunization." (PMID 28726788, 2017). "The elimination of XBP1 splicing or knockdown of CREBH is detrimental to parasite development, indicating a beneficial role of the host UPR for Plasmodium in hepatocytes infection." (PMID 28883998, 2017). "The survival of the xbp-1(zc12);mir-233(n4761) double mutants was comparable to that of the xbp-1(zc12) mutant worms after PA14 infection." (PMID 25569229, 2015).